CD4 (CD4 molecule)
Diseases named in the same sentence as CD4 in open-access papers (continued):
Sharing a sentence is not in itself a finding about the gene and the disease.
cancer (continued). "In analyzing the association of human cancers with immune cells and chemokines, we found that CDCA8 expression was positively correlated with human immune cells Act-CD4 (rho = 0.465, p < 0.01), Th2, MeM-B and chemokines CCL in PCa." (PMID 35449575, 2022). "We noticed that the infiltration levels of CD4+ T cells, CD8+ T cells, NK cells, cancer-associated fibroblasts, and endothelial cells increased with the elevation of risk scores." (PMID 36035178, 2022). "In CCA, CD8+ and CD4+ T lymphocytes represent the majority of TILs and are mostly sequestered around the cancer cells." (PMID 35392957, 2022). "In cancer settings, CD4+CD8+ cells were shown to produce IL-4 themselves, thus probably promoting the induction of IL-4-related programs." (PMID 35222424, 2022). "Necrotic cancer cells attract and activate dendritic cells (DCs) that can migrate to lymph nodes and cross naive CD4+/CD8+ T cells in search of cancer antigens." (PMID 36185996, 2022). "At the same time, DTYMK influenced the infiltration of B cell, CD8+ T cell, CD4+ T cell, macrophage, neutrophil and dendritic cells in several cancers." (PMID 35903153, 2022). "Overexpression of LMNB1 generally predicted poor prognosis for cancer patients and suggested high level of CD4+ Th2 cell infiltration." (PMID 35241075, 2022). "The proportion of regulatory T cells CD4 Memory, T cells CD4 naïve, and Macrophages M1 was relevant to the PIPM risk score of most cancer types." (PMID 35620284, 2022). "NKG2D belongs to the C-type lectin-like activated receptor, which is expressed on NK cells, CD8+T cells, and some autoreactive or immunosuppressive CD4+T cells, and can detect and recognize cancer cells." (PMID 36741380, 2022). "CD4+ helper T cells (Th) are a vital component of the immune system responsible for directing other immune cells to eliminate pathogens and cancer." (PMID 35327505, 2022). "The results suggested that the expression of ARPC5 was positively associated with the infiltration level of B cell, CD4+ T cell, CD8+ T cell, neutrophil cell, macrophage cell, and DC cell in most cancer types, especially for KIRC, LGG, PRAD, THCA, and THYM." (PMID 36148220, 2022). "HTLV-1 infected CD4+ TSCM cells can act as a cancer stem cells contributing to the spread and preservation of malignant cells infected by HTLV-1." (PMID 36059484, 2022). "One issue responsible for the shortcomings in cancer immunotherapy is the inability to stimulate helper CD4+ T cells via the HLA class II pathway to generate a potent antitumor response." (PMID 36499557, 2022). "In the present study, CD4+ cells, neutrophils, and DCs were also significantly altered in many cancers with the change of TGM3 expression level." (PMID 36685895, 2022). "AIE and BIE with higher CYT have higher infiltration of anticancer immune cells, such as cytotoxic T cells, M1 macrophages and activated memory CD4+ T cells, and lower infiltration of cancer-promoting immune cells, such as neutrophils and M2 macrophages." (PMID 36361541, 2022). "Among HIV infected women, 88 (71.5%) were on ART at the time of cancer diagnosis, the median CD4-cell count was 365 cells/μl, and 20.3% had severe immune suppression < 200 cells/μL." (PMID 35971100, 2022). "MHCII is associated with survival, increased numbers of CD4+ and CD8+ T -cells in the TILs, and a good response to anti-PD-1 and PD-L1 immunotherapy in some cancers." (PMID 36140182, 2022). "The activated T cells CD4 memory, T cells follicular helper, resting NK cells, M0 macrophages, M1 macrophages, activated mast cells, and neutrophils are mainly expressed in cancer tissues (p < 0.05)." (PMID 35646079, 2022). "All of these immune deconvolution analyses showed that ACAP1 was significantly positively correlated with the level of CD8+ and CD4+ T cells in most cancer types, except DLBC." (PMID 36497434, 2022).
cancer (continued). "Dendritic cells, a type of APC activated by cancer vaccines, can initiate immune cell migration and activation, leading to the activation of antigen-specific CD4/CD8 T cells that can directly attack cancer." (PMID 36199130, 2022). "Overall, we found heterogeneity in our cohort, but donors with previous COVID-19 infection had increased proportions of INFγ-CD4 T-cells specific for the S protein especially after vaccination, with the exception of unvaccinated cancer patients." (PMID 36139625, 2022). "PLWH who initiated ART at a CD4 count of <100 cells/mm3 had a particularly high cancer incidence rate of 526/100 000 PY (95% CI 374–740)." (PMID 34873875, 2022). "The CD8 and CD4 T cells are the key components of the cancer microenvironment, which is strongly related to the occurrence and development of cancer." (PMID 36360212, 2022). "Cancer immunotherapy involves boosting of immune CD4+, CD8+ T cells and B cells to kill or block cancer cells." (PMID 36551617, 2022). "An immunotherapy treatment based on administration of anti-cancer cell immunoglobulins showed efficacy following the expansion of a CD4 T cell subset characterized by expression of CD44, CXCR3, ICOS and the transcription factor T-bet." (PMID 36362027, 2022). "While CD8+ T-cell exhaustion is relatively well described, much less is known about the exhaustion of CD4+ T cells in cancer." (PMID 35784297, 2022). "Exhausted CD4+ T cells also play important roles in regulating and coordinating immune cells in the attack on cancer cells after immunotherapy treatment." (PMID 35053457, 2022). "Critically, cell culture studies demonstrated that DCs acquired preformed p‐MHCII complexes from dying cancer cells through cell‐to‐cell contacts and membrane transfer, which was conducive to the activation of CD4+ T cells." (PMID 35959554, 2022). "This CD4+ subset with cytotoxic activity has been recently further characterized in different human cancers by Jandus group." (PMID 35008422, 2022). "CD4+ T cells that express the FOXP3 transcription factor function as Treg cells that suppress effective immune responses against cancer cells." (PMID 36253752, 2022). "Recent studies have intriguingly shown that CD4+ CTL can directly kill tumors aberrantly expressing MHCII by recognizing neoantigens, new antigens encoded by mutated genes and expressed on cancer cells." (PMID 36231078, 2022). "Lower levels of expression of CD40LG, which is expressed on the CD4+ helper T cells as a co-stimulatory molecule, are observed in cancer patients, indicating an impaired immune response." (PMID 36276933, 2022). "In some cancers, the presence of invasive CD8+ T lymphocytes is associated with improved prognosis, while CD4+ T lymphocytes, myeloid suppressor cells (MDSCs) and T regulatory cells (Tregs) are negatively correlated with survival." (PMID 35473583, 2022). "WNK3 perturbation increased cancer cell death in cancer cell–immune cell coculture conditions and boosted the secretion of cytokines and cytolytic enzymes, promoting antitumor activities in CD4+ and CD8+ T cells." (PMID 36357569, 2022). "The expressions of MYL9 were significantly associated with the infiltration of cancer‐associated fibroblasts, B cell, CD8+T cell, CD4+T cell, macrophage, neutrophil, dendritic cell in different tumors as well as immune markers." (PMID 34729929, 2022). "We also analyzed the correlations between CD93 and B cells, CD8 + T cells, CD4 + T cells, macrophages, neutrophils, and dendritic cells in 32 types of cancer via the TIMER database." (PMID 35242761, 2022). "We observed notably correlations between IGSF10 expression and infiltration levels of CD8+ T cells, CD4+ T cells, neutrophils, myeloid dendritic cells, macrophages and B cells in most cancer types." (PMID 36685968, 2022). "EPIC and TIMER programs showed an opposite correlation between YAP1 expression and infiltration of CD4+ T cells in a few cancer types." (PMID 36479120, 2022).
cancer (continued). "In another study, cancer stage and type were described as one of the critical factors affecting CD4+, CD8+ and NK cell proportions." (PMID 36261500, 2022). "This suggested a positive correlation between RSK4 isoform expression and the relative proportion of B cells, CD4+ T cells, and CD8+ T cells (p < 0.05) among cancer types where high isoform 1 or 2 expression associates with better survival (LGG and KIRC)." (PMID 36498899, 2022). "Lower positivity of PD-L1 on T cells (including CD4 T cells and CD8 T cells) and monocytes were linked to shorter OS in patients with various cancers after ICI treatments (mainly PD-1 inhibitors)." (PMID 36425096, 2022). "Cancer antigen presentation was downregulated in cluster 1, as well as in CD4 T cells, Th22 cells, monocytes, and Treg cells (step 3)." (PMID 36479115, 2022). "In the last 20 years, increasing data have corroborated initial evidence that DCs (or specific subsets thereof) can acquire functional, preformed p‐MHC complexes from cancer cells to prime both CD4+ and CD8+ T cells against cancer." (PMID 35959554, 2022). "Recent studies have shown that CD4+ T cells can target cancer cells in a variety of ways, either directly by killing cancer cells through cytolysis mechanisms or indirectly by regulating the TME." (PMID 36039642, 2022). "Co-culturing human CD4+ T cells with IDO-expressing DCs or cancer cells increases the differentiation of CD4+ CD25+ FoxP3+ Treg cells with potent suppressor function." (PMID 36269001, 2022). "In support of this, we found decreased MDSC numbers, and increased numbers of CD4+ T cells and natural killer T (NK-T) cells in lungs from cancer-bearing mice treated with S100A8." (PMID 35655772, 2022). "Based on EPIC algorithm, the low-risk subgroup had a higher proportion of B cells, CD4+ T cells, and CD8+ T cells, while cancer-associated fibroblasts (CAFs) were shown to be significantly greater in high-risk patients." (PMID 35711437, 2022). "In this review, we provide an overview of the multifaceted role of different CD4+ T cell subsets in cancer immune response and their contribution during cancer therapies." (PMID 35008422, 2022). "Ultimately, the goal of a cancer vaccine is to aggressively activate the CD8+ T cell pathway, which is mediated by CD4+ T cells, overcoming self-tolerance and immune suppression and resulting in cancer cell eradication." (PMID 36552988, 2022). "TCF19 expression level was significantly related to the CD4 memory-activated cells in 14 kinds of cancers." (PMID 36111242, 2022). "Overall, these findings emphasize the possibility of exploiting the functions of CD4 CTLs in cancer immunotherapy, as discussed in more detail in Section 5 of this Review." (PMID 35572552, 2022). "While there was no trend in the relationships between PLR and CD3+CD8+ T-cells, CD3+CD4+ T-lymphocyte infiltration in the cancer area was positively correlated with PLR (P = 0.013)." (PMID 36217150, 2022). "Over the past decades, CD4+ T cells have been considered as a supporting actor in the fields of cancer immunotherapy." (PMID 35008422, 2022). "A total of 125 target genes were utilized in our study, comprising 78 in macrophages (cancer) and 47 in naïve CD4 + T cells (cancer)." (PMID 36221095, 2022). "CD4+ MTCs in the microenvironment can make a rapid and direct immune response to protect the host against the invasion of cancer cells." (PMID 36105107, 2022). "It has been known that CD4+ T cell subsets play an important role in cancer immunity, including Th1, Th2, and regulatory T (Treg) cells." (PMID 39282149, 2022). "Using depletion experiments and knock-out mice, it was shown that the MDSC-derived IL1-β triggers IL17 production by CD4+ T cells, limiting the anti-cancer efficacy of 5-FU." (PMID 35742825, 2022). "IL-2 has been shown to expand T effector cells for anti-microbial/anti-cancer immunity, while IL-2 can also induce or grow CD4+ CD25+ Foxp3+ regulatory T cells for immune regulation or tolerance." (PMID 35765887, 2022).
cancer (continued). "The CCNA2 expression is positively correlated with Th2 cell infiltration and negatively correlated with CD4+ central memory and effector memory T-cell infiltration in different cancer types." (PMID 35480884, 2022). "CD4+ Th cells play a critical role in initiating and maintaining adaptive immune responses against cancer." (PMID 35309296, 2022). "Collectively, these results showcase the antitumor function of TSLP and CD4+ T cells, which can be a promising therapeutic strategy for cancer immunoprevention and treatment." (PMID 36467403, 2022). "Standardized incidence ratios (SIR) for ICC and BC, and incidence rates for all three cancers were calculated overall and for specific sub-populations according to nadir CD4 cell count, HIV transmission category, HIV diagnosis period, and HCV coinfection." (PMID 35333883, 2022). "Our oncolytic cancer vaccine treatment induced a modest downregulation of the CD4+ T cells in both treated and untreated tumors in line with the increase of CD8+ T cells." (PMID 35314027, 2022). "A central role of both conventional and unconventional CD4+ and CD8+ T cells have been described in TB infection and cancer including complementary as well as overlapping functions of CD4+ and CD8+ T cells." (PMID 36591229, 2022). "In the invasive front, we found a higher density of CD3 and CD4 cells in less advanced cancers, i.e., in T1-T2 CRC and in lower TNM stage (TNM-I vs TNM-II and TNM-I vs TNM-III)." (PMID 36526699, 2022). "CD4+ T cell responses were more readily detectable compared with CD8+ T cell responses in both patients with cancer and HDs." (PMID 35732350, 2022). "TNFRSF4 was first discovered on the surface of activated CD4+ T cells, which played a vital role in immune regulation in multiple cancers as a crucial immune checkpoint." (PMID 35562682, 2022). "Here, to our knowledge, we are the first to report that IDO1 inhibition via epacadostat increased migration of NK and CD4+ T cells towards cancer cells." (PMID 35359980, 2022). "Previous studies have already demonstrated the multifaceted direct and indirect role and involvement of CD4+ T-cells in anti-cancer immunity." (PMID 35565389, 2022). "The results revealed that the AR score was positively correlated with infiltration level of TAMs, and negatively associated with natural killer cells, dendritic cells (activated), CD8+ T cells, naive CD4+ T cells, and lymphocytes in pan-cancer." (PMID 36479101, 2022). "We show that PD-1+CD39+ memory CD4 T cells are enriched in the circulation of cancer patients in comparison with healthy individuals." (PMID 35954341, 2022). "Of note, CD4+ T cells have been demonstrated to have anti-cancer functions outside their role in stimulating cytotoxic immune cells in cancer." (PMID 35565302, 2022). "NPC tissues are massively invaded by T-lymphocytes, particularly of CD4-type, and their interplay with the cancer cells has been suggested to play a role in pathogenesis." (PMID 35938161, 2022). "The present study revealed that NOL7 expression was significantly correlated with the infiltration levels of several types of immune cells, including B cells, CD8+ T cells, CD4+ T cells, macrophages, neutrophils, and DCs, in many cancers." (PMID 36077008, 2022). "In general, SPA17 was positively correlated with the level of immune infiltration of many kinds of infiltrating cells, such as MDSC, progenitors of lymphoid, CD8+ T cell, and CD4+ T cell in various cancers." (PMID 35592314, 2022). "EZH2 expression revealed a positive relationship with the degree of CD8 + T cell infiltration in 20 cancers, macrophages in 12 cancers, CD4 + T cells in 18 cancers, DCs in 19 cancers, and neutrophils in 24 cancers." (PMID 35659256, 2022). "This transcript had previously been identified in cancer cell lines and healthy control CD4+ T cells." (PMID 35289316, 2022). "Instead, the B-MF transfer significantly decreased the frequency and numbers of IFNγ-expressing CD4+ T cells in both cancer models." (PMID 36104343, 2022).
cancer (continued). "By restricting the Ca2+-nuclear factor of activated T cells 1 (NFAT1) signaling pathway in CD4+ T cells, glucose deprivation additionally reduces anti-cancer activities of intratumoral T helper 1 (Th1) CD4+ T cells." (PMID 36072596, 2022). "TNFR2+ CD4 cancer T-cell frequencies were lowered in response to the treatment and the ratio of Tregs/Teffs was restored compared to healthy controls, confirming the potential of antagonistic TNFR2 antibodies in cancer therapy." (PMID 35681583, 2022). "In several cancers expressing MHC II, the intrinsic expression of MHC II in cancer cells is a target directly identified by CD4 + T cells and is a marker of good cancer prognosis." (PMID 35879796, 2022). "We also found that anti-cancer activity after treatment with anti-PD-1 antibody, CC-01 or CC-01 + anti-PD-1 antibody was boosted by CD4+ T cell deletion, suggesting that CD4+Treg decrease was important factor in immunotherapeutic effect." (PMID 35058524, 2022). "The antigen-loaded iDCs are then stimulated by specific cytokines to maturate before injecting them back into the patient, where the mature DCs can present cancer antigens to CD4+/CD8+ T cells, inducing a sustained antitumor response." (PMID 36551661, 2022). "Peptide cancer vaccines also stimulated CD4 T cells with cytotoxic capacity in prostate cancer patients after an AE37 vaccine, a HER2 hybrid polypeptide." (PMID 35572552, 2022). "Deficient CD4( +) T cell help can reduce the response of CTLs and maximizing CD4( +) T cell help can improve outcomes in cancer immunotherapy." (PMID 35123499, 2022). "The function of CD4+ effector memory T (TEM) cells in cancer is complex, and is often dysregulated within the TME." (PMID 36045676, 2022). "We further analyzed the relationship between NCBP2 expression with macrophages and CD4+ T cell infiltration levels in diverse cancer types using the TIMER 2.0 database." (PMID 36010268, 2022). "where RAD51 was positively correlated to T cell CD4+ Th1, T cell CD4+ TH2, and common lymphoid progenitor scores in most of the cancer types, especially T cell CD4+ TH2 which was strongly correlated with RAD51 in most of the cancer types." (PMID 35359409, 2022). "Recent studies using RNA sequencing in human cancers have reported cytotoxic characteristics of CD4+ T cells, which express cytolytic molecules such as granzymes, perforin, and granulysin in the tumors and circulation of cancer patients." (PMID 36613591, 2022). "The preferential activation of CD4 T cells using antigen-LAMP1 fusion proteins has been shown previously in other cancers." (PMID 35651802, 2022). "Regarding the stage, 77% cells in cancer associated with stage III/stage IV, including 22.8% of naïve CD4 + T cell, 13.9% of macrophage and 4% of Treg." (PMID 36221095, 2022). "The higher number of T cells, especially CD8+ T cells, memory cells, and CD4+ Th1 cells, can produce a better prognosis in some cancers." (PMID 35627227, 2022). "High DTYMK expression was positively or negatively correlated with immune cell infiltration, including B cell, CD8+ cell, CD4+ T cell, macrophage, neutrophil and dendritic cell, depending on the type of cancers." (PMID 35903153, 2022). "Previous studies have shown CD4+ T-cell-mediated immune response decreases in subjects who develop cancer precursor lesions or cancer due to a persistent HPV infection." (PMID 36560637, 2022). "In this context, several cancer-vaccine approaches targeting CD4+ T cell response have offered promising results in clinical trials." (PMID 35008422, 2022). "Herein, we demonstrate that CD4+ T helper (Th2) cells directly block spontaneous breast carcinogenesis by inducing the terminal differentiation of the cancer cells." (PMID 35657353, 2022). "Reptin had a meaningful interaction with the immune infiltration of CD4+ Th1 cells and immune modulator genes in multiple cancer types." (PMID 35754815, 2022).